HKDC1 (hexokinase domain containing 1)
Diseases named in the same sentence as HKDC1 in open-access papers (continued):
Sharing a sentence is not in itself a finding about the gene and the disease.
tumor (continued). "Importantly, patients with elevated HKDC1 levels in their tumor tissues often experience poorer prognoses." (PMID 40124623, 2025). "Knockdown of HKDC1 significantly suppressed tumor growth, whereas overexpression accelerated it." (PMID 40209953, 2025). "Given the crucial role of immune checkpoints in enabling immune evasion, these findings suggest that HKDC1 may be integral to the interplay between tumor cells and the immune system." (PMID 40124623, 2025). "The ability of HKDC1 to modulate these essential cellular processes indicated its potential as a prognostic indicator and as a promising target for therapeutic strategies aimed at reactivating apoptosis in tumor cells." (PMID 41049000, 2025). "CircVMP1 upregulates HKDC1, driving increased glycolysis and disease progression while contributing to chemoresistance, compromising therapeutic efficacy and underscoring its role in tumor aggressiveness." (PMID 41049000, 2025). "Furthermore, HKDC1 affects the tumor microenvironment by inhibiting immune cell infiltration and promoting tumor immune evasion, such as enhancing CD8+ T cell exhaustion and PD-L1 mediated immune escape." (PMID 41049000, 2025). "HKDC1 silencing reduces tumor growth and improves chemotherapy response." (PMID 40977684, 2025). "Additionally, we observed a prevalent pattern of HKDC1 copy number deletions across the majority of tumor types, with a minority of samples exhibiting copy number gains." (PMID 40124623, 2025). "This implies that HKDC1 could be instrumental in influencing the immune landscape within the tumor microenvironment." (PMID 40124623, 2025). "In addition, the expression of HKDC1 was detected by testing the tumour samples of PAAD patients and paired paracancerous samples, and HKDC1 was found to be significantly highly expressed in the tumours." (PMID 38434978, 2024). "The findings indicate that the elevated levels of HKDC1 coincide with increased expression of immune checkpoints, resulting in a decline in the body's immune capacity and hindering the antigen presentation process in tumor immunity." (PMID 38434978, 2024). "Furthermore, we explored the correlation between HKDC1 and the tumor microenvironment (TME), as well as immune checkpoints and the responsiveness to drugs." (PMID 38434978, 2024). "The data above indicates that HKDC1 might suppress immune reactions in the tumor microenvironment by influencing immune cells." (PMID 38434978, 2024). "Notably, IHC analysis of 50 clinical HCC tumor samples showed that HKDC1 expression levels were positively correlated with STAT1 phosphorylation and PD-L1 protein levels." (PMID 38351096, 2024). "These cumulative data suggested that HKDC1 expression could enhance tumor immune evasion independently of its hexokinase function." (PMID 38351096, 2024). "A decrease in the infiltration of immune cells could result in diminished anti-tumor effects, potentially accounting for the unfavorable prognosis observed in patients exhibiting elevated levels of HKDC1 expression." (PMID 38434978, 2024). "HKDC1 has been reported to promote glycolysis and tumor progression in gastric cancer." (PMID 38434978, 2024). "To investigate whether HKDC1 hexokinase function in glycolysis plays a role in its promotion of tumor-infiltrating CD8+ T cell exhaustion, we used AlphaFold2 to predict the HKDC1 protein structure and identify possible catalytic sites." (PMID 38351096, 2024). "We observed single LF, NT5DC3 protein, or HKDC1 antibody treatment could partially suppress the tumor growth." (PMID 36855062, 2023). "The results revealed the possibility of HKDC1 as a new prospective target for tumor treatment." (PMID 36518326, 2022). "Moreover, mice that developed LC with NASH had >100-fold higher HKDC1 mRNA expression in the liver tissue (non-tumor regions) than controls, with corresponding enhanced HKDC1 protein expression." (PMID 35902556, 2022).
tumor (continued). "Suppression of the EBV genome inhibited the expression of the LMP1/PGC1β/HKDC1/OGG1 signaling pathway, forming a positive feed forward loop for the generation of ROS, hence inhibiting the EBV genome and subsequent EBV-associated tumor development." (PMID 33423158, 2021). "The results indicate that the expression of HK2 and/or HKDC1 may contribute to tumor growth in ENKTL cells." (PMID 32203147, 2020). "We investigated the potential role of HKDC1 in ENKTL tumor growth." (PMID 32203147, 2020). "Furthermore, the expression of PGC1β and HKDC1 significantly increased metastatic colony formation and tumor spots in the lung." (PMID 31058090, 2019). "We first measured mRNA expression of PGC1β and HKDC1 from the tumor tissues." (PMID 31058090, 2019). "Our preliminary results show that HKDC1 contributes to both endocrine and chemo resistance, and the inhibition of HKDC1 activity by either chemical or biological method significantly suppresses the tumor growth, and this investigation is still in process." (PMID 31058090, 2019). "On the other hand, knockdown of PGC1β and HKDC1 significantly deceased tumor growth." (PMID 31058090, 2019). "Furthermore, an in vivo xenograft tumor development study was employed to investigate the effect of HKDC1 on tumor growth and mouse survival." (PMID 31058090, 2019). "Our results showed that PGC1β protein expression in tumor and metastatic tissues was increased to 168 and 234%, respectively, compared to normal tissues, while the HKDC1 protein expression in tumor and metastatic tissues were increased to 214 and 321%, respectively, compared to normal tissues." (PMID 31058090, 2019). "However, to date, the question of whether HKDC1 exerts its influence across different tumor types through shared molecular mechanisms remains unanswered." (PMID 40124623, 2025). "We next investigated whether ACTA2 was also involved in HKDC1-mediated tumor immune escape." (PMID 38351096, 2024). "Our findings showed that the HKDC1 sequence is highly identical with that of the other isoforms, with the only difference being in the last eight aa in the C-terminal, indicating that the last eight aa may play an important role in tumor growth." (PMID 32203147, 2020). "Overexpression of the last eight aa of HKDC1 at the C-terminal (HKC8) truncates significantly suppresses tumor growth and results in dissociation of HKDC1 from vascular endothelial growth factor 1 (VDAC1), indicating that HKC8 may be a novel antitumor target for ENKTL treatment." (PMID 32203147, 2020). "In addition, the PGC1β had a stronger effect than HKDC1 on in vivo tumor growth." (PMID 31058090, 2019). "This study aimed to investigate HKDC1 expression in CRC and evaluate its effects on tumor growth, migration, and patient prognosis." (PMID 40209953, 2025). "Overexpression of RCOR1 significantly reversed the inhibitory effects of HKDC1 knockdown on CRC proliferation and migration, while silencing RCOR1 mitigated HKDC1's pro-tumor effects." (PMID 40209953, 2025). "HKDC1 expression was significantly elevated in the intestinal mucosa of CRC patients compared to HC and in paired tumor versus normal tissue of the same CRC patients." (PMID 40110992, 2025). "This study aims to explore HKDC1 expression in CRC and its effects on tumor growth, migration, glycolysis, and EMT, as well as the underlying molecular mechanisms." (PMID 40209953, 2025). "Furthermore, the ESTIMATEScore of patients exhibiting elevated HKDC1 levels demonstrated a downward inclination, suggesting that patients with heightened HKDC1 expression may possess increased tumor purity, consequently leading to a heightened level of malignancy." (PMID 38434978, 2024). "Considering that the mechanisms of drug action for HKDC1 and IGF2BP3 differ significantly, the potential of drugs targeting both is likely to be more efficient than targeting independent mechanisms in the tumor cell." (PMID 39164728, 2024).
tumor (continued). "To this end, we assessed the HT29 implantation tumor model in immune-competent C57BL/6 mouse by LF, NT5DC3 protein, or HKDC1 antibody or combination treatment both in normal and diabetic mice." (PMID 36855062, 2023). "In contrast, overexpression of either SOD2 or OGG1 suppresses oxidative stress-induced EBV DNA damage, thus preventing the HKDC1 interruption-induced suppression of EBV and tumor growth." (PMID 33423158, 2021). "The upregulated HKDC1 leads to increased mitochondrial function through its binding with VDAC1, favoring glycolysis and tumor growth." (PMID 33423158, 2021). "Our results suggested that knocking-down HKDC1 suppressed the PGC1β/OGG1 signaling pathway in addition to the replication of EBV and tumor growth in a mouse model." (PMID 33423158, 2021). "The results showed that AGL, SLC16A3, and MIOX were significantly high expressed in tumor samples, whereas HKDC1 and ALDH7A1 were significantly low expressed in tumor samples." (PMID 33991070, 2021). "Our preliminary data showed that HKDC1 expression is highly upregulated in ENKTL cells and HKDC1 knockdown significantly suppresses ENKTL tumor growth, indicating that HKDC1 plays an important role in ENKTL tumor development." (PMID 32203147, 2020). "In our study, we also observed that HKDC1 promoted the proliferation, invasion and EMT capacity in vitro and tumor growth in vivo." (PMID 32943998, 2020). "Our results show that HKDC1 is highly expressed in ENKTL and is involved in cell proliferation and tumor growth." (PMID 32203147, 2020). "We show that delivery of Tf-D-HKC8 peptide dissociates HKDC1 from VDAC1, induces mitochondrial dysfunction and oxidative stress, and subsequently suppresses tumor growth." (PMID 32203147, 2020). "Further validation using a paired Student’s t-test confirmed this upregulation, revealing a statistically significant increase in HKDC1 expression levels in tumor tissues compared to adjacent normal tissues." (PMID 40124623, 2025). "Additionally, HKDC1 facilitates tumor immune escape by recruiting cytoplasmic STAT1 to IFNGR1, thereby revealing its critical role in the tumor immune microenvironment and providing theoretical support for combined immunotherapy." (PMID 40692442, 2025). "HKDC1 demonstrates consistent overexpression across malignancies, functioning as a key oncogene, driving the growth of tumor cells, migration, invasion, glycolysis, EMT, and tumor formation." (PMID 41049000, 2025). "We found that STAT1-Y701 phosphorylation was obviously decreased in IFNγ-stimulated HCC cells with HKDC1 knockdown compared to that in stimulated NTC controls, as well as in YAP5SA-induced HCC-bearing HKDC1 KO mice relative to tumor-bearing WT mice." (PMID 38351096, 2024). "Although normal tissues also expressed HKDC1 protein, HKDC1 protein expression was more evident in PC tissues, mainly located in tumor cells rather than in the stroma." (PMID 36834681, 2023). "We recently found that PGC1β regulates tumor growth and metastasis through a lactate dehydrogenase A (LDHA)-mediated glycolytic metabolism, as well as through the expression of SREBP1-mediated hexokinase domain component 1 (HKDC1)." (PMID 33423158, 2021). "Furthermore, it was shown to upregulate the expression of HKDC1 through the activation of SREBP1, resulting in increased mitochondrial function and glucose metabolism, thus favoring tumor growth." (PMID 33423158, 2021). "HKDC1 expression potentiates the permeability transition pore by interacting with VDAC1, subsequently increasing glucose uptake and promoting cell proliferation and tumor growth." (PMID 31058090, 2019). "HKDC1 is located on the mitochondrial membrane and regulates the permeability transition pore opening by binding with VDAC1, subsequently modulating glucose uptake, cell proliferation, and tumor growth." (PMID 31058090, 2019).
tumor (continued). "Furthermore, we assessed the tumor microenvironment using the ESTIMATE algorithm and observed that the stromal score, immune score, and ESTIMATEScore were comparatively reduced in the HKDC1 high-expression group compared to the HKDC1 low-expression group." (PMID 38434978, 2024). "Furthermore, HKDC1 interruption-mediated mitochondrial dysfunction forms a positive feed forward loop for ROS outbreak, subsequently suppressing EBV replication and LMP1/PGC1β signaling pathway-mediated tumor growth." (PMID 33423158, 2021). "However, ApcMin/+‐Hkdc1∆IEC mice showed fewer lesions larger than 0.5 mm, suggesting that HKDC1 may influence tumor growth rather than initiation." (PMID 40110992, 2025).
infection (1 paper, 2020). The state of being infected such as from the introduction of a foreign agent such as serum, vaccine, antigenic substance or organism. "The results indicated that shHKDC1 decreased HKDC1 mRNA levels to 21%, while infection of HKDC1-ΔN15a, HKDC1-ΔC15a, and HKDC1-ΔC8a increased HKDC1 mRNA to 236%, 219%, and 251%, respectively, compared with the CTL group." (PMID 32203147, 2020). "The findings showed that HK activity in the shHKDC1 group decreased to 54%, while infection of HKDC1-ΔN15a, HKDC1-ΔC15a, and HKDC1-ΔC8a increased HKDC1 activity to 136%, 131%, and 142%, respectively." (PMID 32203147, 2020).
inflammation (1 paper, 2025). Aberrant reaction of the microcirculation characterized by movement of fluid and leukocytes from the blood into extravascular tissues. "Mechanistically, HKDC1 binds to ATPB and antagonizes the ubiquitinase Murf1, thereby leading to increased expression of ATPB and activation of the NF-κB signaling pathway, which promotes renal inflammation." (PMID 40520008, 2025).
metabolic disorder (1 paper, 2023). "Overall, VLPVPQK could alleviate the metabolic disorder of hepatocytes by elevating the glucose uptake and eliminating the ROS, while the HKDC1 and AKR1B10 genes might be the potential target genes and play important roles in the process." (PMID 37444365, 2023).
HKDC1 also shares sentences with these, for which no sentence is quoted: breast tumor (3 papers); T-cell lymphoma (3); cholangiocarcinoma (2); lymphoma (2); rectal adenocarcinoma (2); acute myeloid leukemia (1); adrenocortical carcinoma (1); alcoholic liver diseases (1); colon adenocarcinoma (1); diffuse large B-cell lymphoma (1); fatty liver disease (1); gastric diseases (1); glioblastoma (1); glioma (1); kidney chromophobe (1); mesothelioma (1); ovarian carcinoma (1); pancreatic ductal carcinoma (1); prostate adenocarcinoma (1); prostate carcinoma (1); retinal degeneration (1); testicular germ cell tumor (1); thymoma (1); thyroid carcinoma (1); thyroid tumor (1); Usher syndrome (1); uterine corpus endometrial carcinoma (1); uveal melanoma (1).